TNF (tumor necrosis factor)
Diseases named in the same sentence as TNF in open-access papers (continued):
Sharing a sentence is not in itself a finding about the gene and the disease.
atherosclerosis (continued). "As another representative effector molecule of Th22 cells, TNF-α was considered to potently promote atherosclerosis in mice and humans." (PMID 24312440, 2013). "Evidence shows that TNF-α is a key contributor in the development, progression, and complications of atherosclerosis." (PMID 24381514, 2013). "Inflammatory mediators, such as tumor necrosis factor-α (TNF-α), interleukin (IL)-6 and IL-1, up-regulated in OA, participate in the pathophysiology of atherosclerosis." (PMID 24711757, 2013). "Our previous atherosclerosis-related model was demonstrated in TNF-α stimulated co-culture of EC and SMC obtained from umbilical veins." (PMID 24010774, 2013). "TNF (tumor necrosis factor) plays a key role in increasing the expression of inflammation related genes in atherosclerosis, and expression is increased in brain during ischemia or in patients who suffer intracerebral hemorrhage." (PMID 23874591, 2013). "TNF-α affects the development of atherosclerosis at the fatty streak stage, and cleavage of TNF is an important step in activating the proatherogenic properties of TNF-α." (PMID 22577254, 2012). "We have also previously reported reduced TNF-α in atherosclerotic lesions that accompany the reduced atherosclerosis following B cell depletion by anti-CD20 monoclonal antibody treatment." (PMID 22238605, 2012). "In summary, these findings suggest that contraceptive therapy impacts the function of cells (MDMs) that play crucial roles in immunity and atherosclerosis, modifying the release of TNFα." (PMID 22284681, 2012). "Immune-activated macrophages express a variety of inflammatory genes, such as iNOS, COX-2, TNF-α, and IL-1β, which are major contributing factors in the pathogenesis of atherosclerosis." (PMID 23243449, 2012). "TNF is a major pro-inflammatory cytokine involved in the pathogenesis of atherosclerosis and many other inflammatory diseases." (PMID 23285008, 2012). "Nevertheless, the absence of carotid IMT progression enhances the potential usefulness of the TNF-alpha blocker therapy to decrease the accelerated atherosclerosis observed in patients with RA." (PMID 22899879, 2012). "Tumor necrosis factor-α (TNF-α) is a key inflammatory cytokine involved in the progression of atherosclerosis by activating NF-κB signaling." (PMID 22991685, 2012). "In regard to vascular biology in particular, TNFR2 seems to be crucial for both TNFα-induced atherosclerotic lesions in mouse models for atherosclerosis and leukocyte interaction with the endothelium." (PMID 23079185, 2012). "NF-κB binds to specific sites in the promoter region of target genes and apparently mediates TNF-α-induced activation of endothelial cells by transiently inducing the genes coding for adhesion molecules and atherosclerosis ‐." (PMID 22536886, 2012). "Inactivation of the Lrp1 intracellular NpxYxxL motif enhances post prandial dyslipidemia and atherosclerosis, and increases proapoptotic effects via increased secretion of TNFα in macrophages." (PMID 22384159, 2012). "Monocytes/macrophages infiltrate atherosclerotic lesion areas and increase the expression of inflammatory genes, such as TNF-α, IL-1β and iNOS, which play an important role in development and progression of atherosclerosis." (PMID 23243449, 2012). "TNFα is secreted by mature macrophages and endothelial cells during the progression of atherosclerosis." (PMID 22093181, 2011). "The cytokines TNF-α, IL-1β IL-6, and IL-8 are important in vascular inflammation and atherosclerosis." (PMID 21249123, 2011). "The pro-inflammatory cytokines TNF-α, IL-1β, IL-6, and other acute phase proteins such as serum amyloid A (SAA) and C-reactive protein (CRP) have been associated with atherosclerosis or increased risk of cardiovascular disease." (PMID 21249123, 2011). "Other studies have investigated the ratio of TNF to adiponectin and the consequences for inflammation and atherosclerosis." (PMID 21829524, 2011).
atherosclerosis (continued). "Since in a variety of vascular diseases including atherosclerosis, TNF-α level is increased in the lesion site and contributes to vascular inflammatory process, we then examined the effect of HMC05 on TNF-α-treated endothelial response." (PMID 19736220, 2011). "We showed previously that mast cell-derived TNF-α played negligible roles in atherosclerosis and abdominal aortic aneurysms (AAA)." (PMID 21264293, 2011). "diHPA exerted anti-inflammatory properties by reducing the secretion of pro-inflammatory cytokines, TNF-α, IL-1β and IL-6, involved in the early stages of atherosclerosis from lipopolysaccharide (LPS)-stimulated human peripheral blood mononuclear cells (PBMC)." (PMID 21272305, 2011). "C-Reactive Protein is a marker of inflammation and atherosclerosis regulated by Interleukin-6 (IL-6) and Tumor Necrosis Factor-α (TNF-α), which secretions dose-dependently decreased in presence of vitamin D." (PMID 20937091, 2010). "These chemokines are important modulators inflammation that are secreted from adipose tissue and are responsive to the pro-inflammatory cytokine TNF-α thus providing a possible link between inflammation in adipose tissue and the progression of atherosclerosis." (PMID 19781706, 2010). "TNF-α was chosen as the pro-inflammatory stimulus since it is an important cytokine in the progression of atherosclerosis wherein it exerts pro-inflammatory effects on endothelial cells, smooth muscle cells and macrophages." (PMID 19781706, 2010). "Monocytes, their progeny such as dendritic cells and osteoclasts and products including tumor necrosis factor (TNF)-α, interleukin (IL)-1α and IL-1β play important roles in cancer, inflammation, immune response and atherosclerosis." (PMID 19715605, 2009). "Both in vitro and in vivo experiments have shown the receptor to be important in the initiation of atherosclerosis and to be up-regulated by pro-atherogenic factors, e.g. shear stress, tumor necrosis factor (TNF)-α, and oxLDL itself." (PMID 19997643, 2009). "In atherosclerosis, TNF is generally considered to promote plaque growth and progression since disease induction in TNF deficient mice resulted in reduced development of atherosclerotic lesions as well as their reduced progression towards more advanced stages." (PMID 19582157, 2009). "The P38 MAPK pathway is activated by inflammatory cytokines such as TNF-α, IL-1 and IL-8, which are known to be increased in atherosclerosis and ischemic heart disease." (PMID 18778461, 2008). "The present observation that vascular expression of TNF-α and TNF receptors precedes plaque formation in this mouse model of atherosclerosis provides some indirect support for a pro-atherogenic role of TNF-α." (PMID 23675033, 2007). "At 16 weeks TNF-α expression in the media was increased more than four-fold as compared with 8 week old mice, and atherosclerosis was widespread." (PMID 23675033, 2007). "Of the various molecular agents of inflammatory response, proinflammatory cytokines, and TNFα in particular, play a major role in the development of atherosclerosis." (PMID 17335569, 2007). "The present study was designed to investigate if vascular TNF-α expression precedes plaque formation in a mouse model of lipid-induced atherosclerosis." (PMID 23675033, 2007). "Another inflammatory marker involved in both the generation and propagation of atherosclerosis is tumor necrosis factor α (TNF-α)." (PMID 16674818, 2006). "Many studies also suggest that smoking induces inflammatory factors (TNF-α, CRP, IL-6, fibrinogen, etc.)that are risk factors for atherosclerosis and cardiovascular diseases." (PMID 16262911, 2005). "Furthermore, transcriptomic profiling identifies 440 differentially expressed genes enriched in lipid metabolism and inflammatory pathways, including lipid and atherosclerosis, NF-κB, and TNF signaling pathways." (PMID 42005321, 2026).
atherosclerosis (continued). "TNFα modulates leukocyte activation and maturation, cytokine and chemokine release, and the generation of reactive oxygen species and nitrogen intermediates in atherosclerosis." (PMID 41527512, 2026). "Joint pathway analysis integrating reversed metabolites with predicted targets consistently prioritized Lipid and atherosclerosis, PPAR-related metabolic regulation, PI3K-Akt/eNOS-associated vascular protection, and inflammation-related signaling (JAK-STAT and TNF/NF-κB)." (PMID 42257022, 2026). "In PE cases, genes were enriched in the lipid atherosclerosis and TNF signalling pathways." (PMID 40672961, 2025). "Rivaroxaban may improve atherosclerosis by reducing TNF-α and IL-6 and interfering with macrophage activation." (PMID 40136627, 2025). "Additionally, keywords such as “tumor necrosis factor-alpha” (2014–2015), “atherosclerosis” (2016–2018), “glucocorticoids” (2017–2019), “inhibition” (2018–2020), and “formulation” (2019–2021), among others, also exhibited significant burst periods." (PMID 40129468, 2025). "As a result, exercise reduces TNFα expression, which eases the progression of atherosclerosis." (PMID 40861271, 2025). "In particular, the nucleotide-binding oligomerization domain (NOD)-, LRR-, and NLR family pyrin domain-containing protein 3 (NLRP3) inflammasome and cytokines such as TNF-α and IL-1 have been identified as significant contributors to the inflammatory processes that drive atherosclerosis progression." (PMID 40006011, 2025). "Subsequent gene ontology analysis revealed these targets were associated with the functional terms inflammatory response, plasma membrane, and ATP binding, whereas KEGG analysis revealed associations with TNF signaling pathway, HIF-1 signaling pathway, and lipid and atherosclerosis terms." (PMID 40963918, 2025). "Endothelial dysfunction molecular markers, including intercellular adhesion molecule-1 (ICAM-1) and tumor necrosis factor-α (TNF-α), which are pivotal factors in the development and pathophysiology of atherosclerosis, exhibit increased levels in individuals with prediabetes." (PMID 40251690, 2025). "Furthermore, p-coumaric acid suppressed the expression of NF-kB, COX-2, tumor necrosis factor-alpha (TNF-α), and interleukin-6 (IL-6), suggesting its potential to mitigate the inflammatory response associated with atherosclerosis." (PMID 41226277, 2025). "Furthermore, radiation increases many inflammatory markers such as tumor necrosis factor, interleukin-6, platelet-derived growth factor, and transforming growth factor, leading to atherosclerosis formation." (PMID 40283126, 2025). "Chronic inflammation and circulating cytokines like TNF-α contribute to atherosclerosis." (PMID 40765607, 2025). "In a study we included, it was shown that Sal B could exert anti-inflammatory activity by inhibiting the STAT3/NF-κB signalling pathway and suppressing the expression of the inflammatory factors IL-1β, IL-6, and TNF-α, thereby attenuating atherosclerosis." (PMID 40606622, 2025). "GO and KEGG enrichment analyses indicated that these targets were significantly involved in biological processes such as aging and response to lipopolysaccharide, and were enriched in pathways including AGE-RAGE, IL-17, lipid and atherosclerosis, and TNF signaling." (PMID 41470792, 2025). "In addition, miR-29c-3p was also involved in the fluid shear stress and atherosclerosis pathway (p 3.35 × 10−5) and the TNF signaling pathway (p 0.003)." (PMID 40867509, 2025).
atherosclerosis (continued). "Heavy metals may disrupt adipocyte differentiation and function, increasing secretion of pro-inflammatory cytokines (e.g., IL-6 and TNF-α) and reducing adiponectin, which amplifies systemic inflammation and atherosclerosis." (PMID 40635894, 2025). "Meanwhile, existing studies have focused more on the effects of STS on pro-inflammatory cytokines, such as IL-6 and TNF-α, while neglecting its effects on adhesion molecules and chemokines, which also play an important role in the inflammatory process of atherosclerosis." (PMID 40017522, 2025). "Functional analysis showed that cytokine−cytokine receptor interaction, graft−versus−host disease, inflammatory bowel disease, Lipid and atherosclerosis, sphingolipid signaling pathway, TNF signaling pathway, and FOXO signaling pathway, etc. play important roles in T2DM." (PMID 40951426, 2025). "TNFα is a key proinflammatory cytokine involved in the development of atherosclerosis." (PMID 40943715, 2025). "The KEGG enrichment analysis results showed that the primary pathways involved included lipid and atherosclerosis signaling pathways, the ErbB signaling pathway, the Toll-like receptor signaling pathway, the TNF signaling pathway, and the PI3K-Akt signaling pathway." (PMID 40238820, 2025). "TNF-α, known for its potent pro-inflammatory effects, not only induces the expression of other inflammatory cytokines and adhesion molecules but also triggers apoptosis of vascular smooth muscle cells, thereby promoting atherosclerosis and plaque instability." (PMID 40475061, 2025). "Among them, three GOBP terms (defense response, response to an external stimulus, and response to chemicals) and four KEGG terms (cytokine–cytokine receptor interaction, lipid and atherosclerosis, malaria, and TNF signaling pathway) were shared across the O2 conditions." (PMID 41199666, 2025). "Proinflammatory cytokines, such as tumor necrosis factor-alpha (TNF-α) and interleukin-6 (IL-6), play a pivotal role in the progression of both RA and atherosclerosis, creating a shared pathological pathway that exacerbates cardiovascular risks in these patients." (PMID 40552192, 2025). "Markers of oxidative stress and inflammation, namely ROS and TNF-α, were also significantly decreased in the P3 group compared with the atherosclerosis control group (K+), further supporting the antioxidant and anti-inflammatory properties of red watermelon extract." (PMID 40699832, 2025). "Furthermore, both lipid and atherosclerosis and the TNF signaling pathway displayed notable degrees of connectivity." (PMID 39440769, 2025). "EAT secretes pro-inflammatory cytokines (such as IL-6, TNF-α) that promote atherosclerosis." (PMID 40776948, 2025). "A cluster of differentiation 40 (CD40) and CD40 ligand (CD40L, costimulatory molecules that belong to the superfamily of tumor necrosis factor (TNF) proinflammatory chemokines are contributory to the burden of atherosclerosis, plaque stability, and prothrombotic effects." (PMID 40573228, 2025). "The intersecting genes were evidently involved in lipid and atherosclerosis, IL-17, TNF, toll-like receptor, NOD-like receptor, apoptosis, calcium, chemical carcinogenesis-reactive oxygen species, phospholipase D, sphingolipid, NF-κB, and PPAR signaling pathways." (PMID 40872501, 2025). "In addition, IH causes systemic inflammation that is marked by increased cytokine levels, including tumor necrosis factor-alpha (TNF-α) and interleukin-6 (IL-6), which worsens endothelial function and accelerates atherosclerosis." (PMID 41426756, 2025).
atherosclerosis (continued). "To evaluate the effect of sodium nitrate on atherosclerosis, we detected inflammatory cytokine expression in mouse aortas by using QPCR and found that the expression levels of IL-1β, IL-6, IL-8, and TNF-α, especially IL-8, were significantly decreased in the sodium nitrate treatment group." (PMID 40110129, 2025). "Treatments like immunosuppressive agents, TNF-α blockers, corticosteroids, and colchicine could influence the rate of atherosclerosis and syndecan-1 levels." (PMID 41578772, 2025). "Biomarkers such as TNF-α, IL-6, and leukotrienes could be used for real-time tracking of atherosclerosis progression, allowing for earlier intervention before clinical symptoms arise." (PMID 40217801, 2025). "The involvement of TNF-α in atherosclerosis can be described through multiple mechanisms." (PMID 40006011, 2025). "KEGG enrichment analysis highlighted the involvement of these genes in key pathways such as PI3K-Akt signaling pathway, AGE-RAGE signaling pathway in diabetic complications, fluid shear stress and atherosclerosis pathway, TNF signaling pathway, and IL-17 signaling pathway." (PMID 41394816, 2025). "The JAK-STAT pathway is important in the development of atherosclerosis by modulating IL-6 and TNF." (PMID 40283183, 2025). "CHD is closely linked to atherosclerosis, which is a chronic inflammatory condition characterized by the involvement of inflammatory mediators such as high-sensitivity C-reactive protein (hs-CRP), interleukin-6 (IL-6), and tumor necrosis factor-alpha (TNF-α)." (PMID 39953634, 2025). "Endurance exercise intervention significantly increased the levels of short-chain fatty acids (SCFAs) in the aorta of mice with western diet (WD) -induced atherosclerosis, thereby reducing the production of aortic TNFα by inhibiting inflammatory signaling pathways." (PMID 40861271, 2025). "Additionally, VCAM-1 expression on EC surface can be significantly enhanced by TNF, IL-1β, and IFNγ during atherosclerosis." (PMID 40454002, 2025). "Additionally, impaired triglyceride metabolism stimulates the secretion of pro-inflammatory cytokines, such as TNF-α, IL-6, and IL-1β, leading to systemic inflammation and endothelial dysfunction—both of which accelerate the progression of atherosclerosis." (PMID 40077648, 2025). "Cardiovascular Disease: The persistent inflammatory state, driven by chronic immune activation and pro-inflammatory cytokine release (e.g., IL-6, TNF-α), is a well-established, powerful driver of atherosclerosis and cardiovascular mortality in dialysis patients." (PMID 41010736, 2025). "Further, KEGG analysis indicated that the inhibitory effect may be related to lipid and atherosclerosis pathway, TNF, apoptosis, PI3k-Akt and IL-17 signaling pathways." (PMID 39965011, 2025). "KEGG enrichment analysis revealed 186 pathways, and the targets enriched in KEGG pathways mainly include the AGE‐RAGE signaling pathway in diabetic complications, Lipid, and atherosclerosis, Fluid shear stress and atherosclerosis, IL‐17 signaling pathway, TNF signaling pathway, etc.." (PMID 41245191, 2025). "Vascular inflammation is known to cause atherosclerosis, so we investigated the impact of GV1001 on the development of vascular inflammation by determining the levels of the major proinflammatory cytokines, such as IL-1β, TNF-α, and IL-6." (PMID 38892314, 2024). "We stimulated RAW264.7 cells and PLEK-knockdown RAW264.7 cells with LPS and TNF-α to observe whether PLEK would influence the atherosclerosis process through the NFκB signaling pathway." (PMID 38716195, 2024). "Bioinformatics analysis indicates that Roxadustat may influence integrin adhesion and affect the TNF and NF-κB signaling pathways, along with lipid and atherosclerosis pathways, potentially reducing inflammation." (PMID 38962312, 2024).